NECTIN4 (nectin cell adhesion molecule 4)
Diseases named in the same sentence as NECTIN4 in open-access papers (continued):
Sharing a sentence is not in itself a finding about the gene and the disease.
cervical cancer (6 papers, 2023 to 2025). A primary or metastatic malignant neoplasm involving the cervix. "In a mouse clinical trial of patient-derived cervical cancers with a range of Nectin-4 expression levels, ADRX-0706 reaches a 73% ORR." (PMID 40697656, 2025). "9MW2821 is the first Nectin-4-targeted ADC to demonstrate antitumor activity in patients with cervical cancer." (PMID 40697656, 2025). "Emerging evidence suggests that Nectin-4 may activate double-strand DNA repair pathways in cervical cancer stem cells, thereby promoting malignant progression." (PMID 40697656, 2025). "Nectin-4 could serve as an effective target for cervical cancer, and Nectin-4-targeting ADCs have already demonstrated promising efficacy in cervical cancer patients." (PMID 40697656, 2025). "This review outlines promising tumor-associated antigens (TAAs) for ADC targeting in cervical cancer and their biological functions, such as human epidermal growth factor receptor 2 (HER2), trophoblast cell surface antigen 2 (Trop-2), mesothelin, nectin cell adhesion molecule 4 (Nectin-4)." (PMID 40697656, 2025). "In the cervical cancer expansion cohort of a clinical trial for a novel Nectin-4-targeting ADC, the detection rate of Nectin-4 expression was 89.67%, and the detection rate of Nectin-4 tumor cell staining intensity of 3+ was 67.82%." (PMID 40697656, 2025). "Tumor-associated antigens (TAAs) with potential for ADC targeting in cervical cancer include TF, human epidermal growth factor receptor 2 (HER2), trophoblast cell surface antigen 2 (Trop-2), mesothelin, and Nectin cell adhesion molecule 4 (Nectin-4)." (PMID 41463185, 2025).
colorectal cancer (6 papers, 2016 to 2024). A primary or metastatic malignant neoplasm that affects the colon or rectum. "Initially identified as a receptor for the measles virus, Nectin-4 mediates viral entry into breast cancer and colorectal cancer cells through endocytic pathways, serving as a primary mediator of viral infection and spread." (PMID 38755613, 2024). "Overexpressed in various cancers such as gastric, breast, lung, urothelial, and colorectal cancers, Nectin-4 is a validated clinical oncology target." (PMID 38755613, 2024). "This lack highlights the importance of our study, as it contributes valuable insights into the prognostic relevance of nectin-4 within the context of colorectal cancer—a topic that warrants further exploration." (PMID 37958883, 2023). "Given the high percentage of colorectal cancer (CRC) cells observed in our study group showing nectin-4 expression, it seems reasonable to consider a clinical trial involving patients with colorectal cancer." (PMID 37958883, 2023). "Nectin4 mCAR-T therapy for subcutaneous xenograft of colorectal cancer in the fully immune-competent mouse model was dose-dependent and exhibited superior anti-tumor efficacy with pretreatment of lymphodepletion." (PMID 36479116, 2022). "A flow-cytometric analysis was conducted to examine the expression of nectin-4 in colorectal cancer cell lines." (PMID 27090874, 2016). "A water-soluble tetrazolium salt (WST) assay was performed to determine the killing activity of rMV-EGFP-SLAMblind in nectin-4-positive colorectal cancer cell lines." (PMID 27090874, 2016). "In conclusion, we have demonstrated the antitumor effects of rMV-SLAMblind against nectin-4-positive colorectal cancer cells, including cells resistant to EGFR inhibitors, indicating that it is a potential novel therapy for colorectal cancers." (PMID 27090874, 2016).
ductal breast carcinoma (6 papers, 2007 to 2023). "To validate the feasibility of using the nectin-4-specific scFv L4 on clinical samples as a diagnostic tool, we further performed immunohistochemistry (IHC) staining of breast ductal carcinoma paraffin-embedded tissue sections with the scFv." (PMID 38288120, 2023). "For example the PVRL-4 gene product, Nectin-4 was found to be undetectable in normal breast epithelium, but expressed in some 60% of ductal breast carcinomas, correlating strongly with basal-like markers." (PMID 23460839, 2013). "E-cadherin is expressed in all subtypes of ductal cancers, whereas Nectin-4 is only expressed in a subset of ductal carcinomas that express basal-like markers." (PMID 17474988, 2007). "Nevertheless, as SaDu and ductal carcinoma of the breast have similar biological and histopathological features, it seems plausible that a higher Nectin-4 expression in SaDu may serve as a favorable prognostic factor." (PMID 37480387, 2023). "Altogether, our data described Nectin-4 as a new protein marker for ductal breast carcinoma." (PMID 17474988, 2007). "However, we found E-cadherin expression in 95% of ductal carcinomas vs 61% for Nectin-4." (PMID 17474988, 2007). "Ductal carcinomas had lower levels of Nectin-3 but not Nectin-4, (Nectin-3: ductal 1534+/−1177 versus other 2581+/−1699, p = 0.6; Nectin-4: ductal 0.30+/−0.15 versus other 0.022+/−0.021, p = 0.074)." (PMID 24386110, 2013).
non-small cell lung carcinoma (6 papers, 2015 to 2026). A group of at least three distinct histological types of lung cancer, including non-small cell squamous cell carcinoma, adenocarcinoma, and large cell carcinoma. "The expression of nectin-2 and nectin-4 has been reported to be associated with a poor prognosis in gallbladder carcinoma and non-small-cell lung carcinoma, respectively." (PMID 25690753, 2015). "In non-small-cell lung cancer, a high level of nectin-4 expression is associated with a poor prognosis, and the serum level of nectin-4 was significantly higher in non-small-cell lung cancer patients than healthy tissue donors." (PMID 25690753, 2015). "Serum Nectin-4 may have diagnostic value for non-small-cell lung cancer (NSCLC)." (PMID 38606099, 2024).
colon cancer (5 papers, 2011 to 2022). "A combination of BCNU and resveratrol-induced apoptosis in 5-FU resistant colon cancer cells by decreasing Nectin-4 expression." (PMID 36553083, 2022). "For example, in colon cancer cells, NECTIN4-overexpressing cells acquired resistance to 5-fluorouracil, but inhibition of NECTIN4 increased cell sensitivity to 5-fluorouracil and induced apoptosis." (PMID 35256687, 2022). "Colon cancer cells exposed to 5-fluorouracil (5-FU, a core drug in CRC chemotherapy worldwide) increased endogenous Nectin-4 expression." (PMID 36553083, 2022).
ectodermal dysplasia-syndactyly syndrome (5 papers, 2020 to 2023). "Mutations in NECTIN4 may cause ectodermal dysplasia-syndactyly syndrome (EDSS1), which is an autosomal disorder." (PMID 32555608, 2020). "We also inoculated primary keratinocytes from a patient affected by ectodermal dysplasia-syndactyly syndrome (EDSS1, OMIM 613573), an autosomal recessive disorder caused by mutations in the nectin-4 encoding gene PVRL4." (PMID 33031460, 2020).
endometrial cancer (5 papers, 2023 to 2026). Primary or metastatic malignant neoplasm involving the endometrium (mucous membrane that lines the endometrial cavity). "Our findings emphasize the importance of Nectin-4 as a novel diagnostic tool and screening marker for assessing endometrial cancer and improving the accuracy of approaches used to predict high-risk endometrial cancer." (PMID 37345201, 2023). "The adhesion molecule Nectin-4 is a new potential therapeutic target for different types of cancer; however, little is known about its diagnosis significance in endometrial cancer (EC)." (PMID 37345201, 2023). "Here, we examined 320 tissue samples from patients with endometrial cancer to determine the relevance of Nectin-4 expression in the diagnosis and prognosis of endometrial cancer." (PMID 37345201, 2023). "However, no studies have been conducted to determine the clinical importance of Nectin-4 expression in endometrial cancer." (PMID 37345201, 2023). "This article provides a focused narrative overview of recent advances in ADCs for the treatment of endometrial cancer, with a primary focus on key targets including Trop-2, HER2, FRα, and Nectin-4." (PMID 42125712, 2026).
lung adenocarcinoma (5 papers, 2011 to 2024). A carcinoma that arises from the lung and is characterized by the presence of malignant glandular epithelial cells. "The rMV‐SLAMblind virus has lost pathogenicity and has been found to have oncolytic effects in human lung adenocarcinoma cells expressing nectin‐4." (PMID 35905293, 2022). "Rac1 is activated by nectin‐4, and in human lung adenocarcinoma, the expression of nectin‐4 activates Rac1 and promotes tumour cell invasion and growth." (PMID 35905293, 2022). "Human lung adenocarcinoma is different from the results of our study because nectin‐4 expression has been reported to be a poor prognostic factor." (PMID 35905293, 2022). "This study demonstrated that gene expression of Nectin‐4 was detected approximately 73% (25 of 34 cases) in canine lung adenocarcinoma and correlated with tumor weight and volume." (PMID 35905293, 2022). "One study has shown that Nectin-4 contributes to the cell growth and proliferation of tumors through the Rac1-signaling pathway in human lung adenocarcinoma cells." (PMID 25888293, 2015). "On the other hand, cytokeratin 19‐fragment (CYFRA21‐1) and carcinoembryonic antigen have been used as tumour markers in human lung adenocarcinoma, and reports indicate that sensitivity increases when these markers are measured simultaneously with serum nectin‐4." (PMID 35905293, 2022). "Furthermore, the association between histological subtypes of lung adenocarcinoma and Nectin‐4 expression levels is important but has not been investigated and needs further investigation." (PMID 35905293, 2022). "Therefore, Nectin‐4 might be a tumor growth factor in canine lung adenocarcinoma." (PMID 35905293, 2022). "We hypothesized that Nectin‐4 gene expression in CPLA occurs at a high frequency, similar to that in human lung adenocarcinomas." (PMID 35905293, 2022).
lymph node metastasis (5 papers, 2020 to 2026). "The expression level of Nectin-4 is significantly associated with cancer cell differentiation, lymph node metastasis, advanced TNM stage, and poor patient prognosis." (PMID 37345201, 2023). "Nectin-4 was highly expressed in 92% of samples and was linked to unfavorable disease characteristics—lymph node metastasis, tumor size and grade." (PMID 37568798, 2023). "Strong Nectin-4 expression was also an independent predictor of disease progression in the high-risk group (pT3 ≤ or presence of lymphovascular invasion or lymph node metastasis) (Hazard ratio, 3.32 [95% confidence interval, 1.20–7.98; p = 0.027])." (PMID 32751328, 2020). "The other patient had moderate Nectin‐4 expression in the lymph node metastasis (H‐score 110) but markedly greater expression in the primary tumour (H‐score 285)." (PMID 40847665, 2026). "Nectin‐4 was detectable by molecular imaging in lymph node metastasis, bone metastasis and lung metastasis in the majority of patients." (PMID 40847665, 2026). "Expression of nectin-4 correlated with T stage and lymph node metastasis in GBC." (PMID 37568798, 2023). "Nectin-4 was expressed in 80.3% of primary SGC with a mean Histo(H-)score of 61.2 and in 90.0% of lymph node metastases with a mean H-score of 75.6." (PMID 37480387, 2023). "Therefore, the current study aimed to investigate the expression of Nectin-4 in a large SGC cohort consisting of primaries and corresponding lymph node metastases and correlating it with clinicopathological data." (PMID 37480387, 2023).
papillary thyroid cancer (5 papers, 2021 to 2022). "TROP-2 and nectin-4 are potential therapeutic targets for ATC undifferentiated from papillary thyroid carcinoma and de novo ATC, respectively." (PMID 35158847, 2022). "NECTIN4 has been reported to promote cancer cell proliferation in tumors, including breast, gastric, and papillary thyroid cancers." (PMID 33808400, 2021). "The involvement of NECTIN4 in tumor progression has been reported in other tumors as well, including gallbladder, breast, gastric, and papillary thyroid cancers." (PMID 33478111, 2021).
urothelial bladder cancer (5 papers, 2021 to 2025). "Nectin cell adhesion molecule 4 (Nectin-4) is a highly innovative and promising treatment target in urothelial carcinoma of the bladder (UC)." (PMID 36139571, 2022). "The IHC results confirmed the protein expression and localization of the NECTIN4 and ERBB2 in the bladder urothelial carcinoma." (PMID 33490264, 2021). "Nectin-4 and MMR could be expressed at different levels in UTUC in respect to urothelial bladder cancer." (PMID 35164713, 2022).
bladder tumor (4 papers, 2020 to 2025). "NECTIN4 mRNA expression has been shown to be enriched in luminal bladder tumors relative to basal bladder tumors." (PMID 40422537, 2025). "The enfortumab antibody binds nectin-4, highly expressed on bladder tumor cells, and induces cell death via vedotin." (PMID 39823053, 2024). "EV is an ADC that targets Nectin-4 that is overexpressed on the surface of bladder tumor cells." (PMID 33019653, 2020). "The antibody-drug conjugates (ADCs) enfortumab vedotin (EV) and sacituzumab govitecan (SG) have demonstrated the ability to provide objective response rates (ORRs) of 44% and 31% in patients with bladder tumor cells that express Nectin-4 and Trop-2, respectively." (PMID 33019653, 2020).
ectodermal dysplasia (4 papers, 2017 to 2023). "EDSS1, a syndrome characterized by ectodermal dysplasia-syndactyly, is inherited in an autosomal recessive manner due to mutations in the NECTIN4/PVRL4 gene." (PMID 37829154, 2023). "The previously reported missense and nonsense/frameshift mutations of nectin-4 hit the ectodomain of the protein-producing ectodermal dysplasia and cutaneous syndactyly of the hands and feet." (PMID 34067522, 2021). "It was demonstrated recently that mutations in NECTIN4 resulted in ectodermal dysplasia-syndactyly syndrome in humans." (PMID 30217189, 2018). "Mutations in PVRL4, which encodes nectin-4, have been found in ectodermal dysplasia syndromes, but Pvrl4 is not thought to be under the control of p63." (PMID 28604778, 2017).
glioma (4 papers, 2019 to 2023). A benign or malignant brain and spinal cord tumor that arises from glial cells (astrocytes, oligodendrocytes, ependymal cells). "Subsequent analysis in TCGA dataset indicated that CD155 was positive associated with CD96, CD226, and Nectin4 in glioma and GBM samples." (PMID 31377744, 2019). "We found that not only common tumors such as lung, ovarian, and gastrointestinal cancers as previously reported, but also glioma, leiomyosarcoma, liposarcoma, gingival carcinoma, nasopharyngeal carcinoma, and laryngocarcinoma highly expressed Nectin4." (PMID 36479116, 2022). "CD155 showed strong positive concordance with CD96, CD226, and Nectin4 in all gliomas and GBM samples from Rembrandt dataset." (PMID 31377744, 2019).
prostate carcinoma (4 papers, 2007 to 2024). A carcinoma that arises from epithelial cells of the prostate gland. "Our objective was to evaluate the efficacy of EV in established prostate cancer (PCa) cell lines and to examine the membranous NECTIN‐4 expression in primary tumours (PRIM) and distant metastases (MET)." (PMID 39072867, 2024). "In accordance with our findings revealing limited NECTIN‐4 expression in prostate cancer metastases, a thorough evaluation of NECTIN‐4 expression as a predictive marker is granted in EV‐treated patients with mCRPC." (PMID 39072867, 2024). "In veterinary medicine, it is known that canine distemper virus uses nectin‐4 as a receptor, and furthermore, it has been reported that nectin‐4 expression is involved in tumour growth in prostate cancer." (PMID 35905293, 2022). "We found 0/23 sera positive for Nectin-4 vs 18/23 for PSA in patients with prostate carcinoma (data not shown)." (PMID 17474988, 2007). "Thus, serum Nectin-4 is not a valuable marker for ovarian and prostate carcinomas." (PMID 17474988, 2007).
serous ovarian cancer (4 papers, 2019 to 2025). "Furthermore, the identification of Nectin-4 as a central gene involved in peritoneal metastasis in high-grade serous ovarian cancer suggests that peptide N4-P10 may be able to reduce metastatic spread by blocking tumor cell adhesion to the mesothelial cells that line the abdominal cavity." (PMID 40075748, 2025). "Increased expression of all the selected genes except NECTIN4 and SNAI1 showed significant correlation with poor clinical outcomes in patients with serous ovarian cancer, but not with the endometrioid subtype." (PMID 34868914, 2021).
small cell carcinoma (4 papers, 2022 to 2024). A neuroendocrine carcinoma composed of small malignant cells which are often said to resemble "oat cells" under the microscope. "Several variant histologies of BC, namely, SCC, ADENO, and small cell neuroendocrine carcinoma, have been shown to express Nectin-4, but those early studies enclosed only small case numbers." (PMID 36139571, 2022). "Further research is needed on nectin‐4 expression and EV's impact on non‐urothelial subtypes, including small cell carcinomas." (PMID 38966765, 2024). "In our report, the first patient was diagnosed with pure small cell carcinoma, a non‐urothelial type with low nectin‐4 expression, significantly reducing EV's effectiveness." (PMID 38966765, 2024). "On the contrary, the expression levels of TROP-2 and NECTIN-4 decreased in small cell carcinoma, even being exceeded by that of HER2." (PMID 35515131, 2022).